CASR (calcium sensing receptor)
Diseases named in the same sentence as CASR in open-access papers (continued):
Sharing a sentence is not in itself a finding about the gene and the disease.
diabetes (continued). "Therefore, CaSR could couple to many G proteins within pancreatic tissue, and this may explain why no overt pancreatic phenotypes (e.g. diabetes, variations in blood glucose or insulin levels) have been reported in patients with GNA11 mutations." (PMID 34077389, 2021).
prostate carcinoma (20 papers, 2009 to 2025). A carcinoma that arises from epithelial cells of the prostate gland. "It has recently been investigated the role of CaSR in lethal prostate cancers, where higher CaSR tumour expression was associated with an approximately 2-fold higher risk for lethal progression, independently of Gleason grade and pathological stage." (PMID 32931488, 2020). "A number of single-nucleotide polymorphisms in CaSR have been identified that exhibit an association with prostate cancer recurrence and lethality." (PMID 29921791, 2018). "A second study assessed genetic variations across CaSR and lethal prostate cancer risk in Caucasian men." (PMID 27625611, 2016). "Third, in a study that correlated primary tumor CaSR expression with the risk for lethal prostate cancer, a higher CaSR tumor expression was associated with an approximately two-fold higher risk for lethal progression." (PMID 27625611, 2016). "Common genetic variations in CaSR were found associated with both higher and lower risk for lethal prostate cancer." (PMID 27625611, 2016). "First, the CaSR Q1011E minor allele, which is common in populations with African ancestry, appeared to be associated with a less aggressive form of prostate cancer among African-American men." (PMID 27625611, 2016). "The calcium sensing receptor is associated with calcification in the prostate cancer." (PMID 35187010, 2022). "Moreover, calcium might act through calcium-sensing receptor in prostate cells (CaSR) since genetic variations across CaSR have been shown to be associated with fatal prostate cancer." (PMID 38187795, 2023). "Unlike suppressed PTHrP secretion by elevated Ca2+ in normal tissue, high Ca2+ concentrations stimulate CaSR to secrete PTHrP in prostate cancer, breast cancer, and lung cancer cells." (PMID 36071984, 2022). "Manganese enhanced Magnetic Resonance Imaging (MEMRI) was able to image human breast or prostate cancer animal models with different intra- and inter-tumour expression levels of CaSR." (PMID 32931488, 2020). "CaSR expression has been previously demonstrated by using immunoblotting in several PCa cell lines and has been shown to be increased in prostate cancer tissues compared to normal prostate." (PMID 32252342, 2020). "The possible therapeutic effect of blocking this receptor has been recently reported by Yamamura and colleagues, who demonstrated that the proliferation and migration of human prostate cancer cells was impaired by the CasR antagonist calcilytics." (PMID 33113952, 2020). "Immunohistochemistry analysis carried out on the pseudometastatic human prostate cancer animal model which progressed quickly, demonstrated high levels of expression of CaSR (score 4-5) either in the lung and intra-abdominal metastatic deposits." (PMID 32931488, 2020). "Manganese contrast enhancement in breast or prostate cancer animal models well correlated with CaSR expression (p<0.01), whereas TRPV6 expression levels appeared not relevant to the Mn uptake." (PMID 32931488, 2020). "We used MDA-MB-231 breast and PC3 prostate cancer cell lines normally expressing both CaSR and TRPV6 at high levels." (PMID 32931488, 2020). "CasR is significantly expressed in advanced and aggressive prostate cancers, such as metastatic castration resistant tumors and neuroendocrine prostate cancers, and a correlation between high CasR expression and decreased survival was observed." (PMID 33113952, 2020). "Further useful investigations aiming to demonstrate the “active role” of CaSR in MEMRI should take into consideration the knockdown/knock-in of CaSR in breast or prostate cancer cells." (PMID 32931488, 2020). "The use of CaSR NAMs was also considered in cases of breast and prostate carcinomas to prevent bone metastases, which are established through a CaSR-mediated signaling." (PMID 31719824, 2019). "In prostate cancer cells, CaSR stimulation transactivates the EGFR, leading to ERK phosphorylation and resultant PTHrP secretion." (PMID 28915604, 2017).
prostate carcinoma (continued). "CaSR mRNA and protein is also detected in the highly bone metastatic prostate cancer cell lines PC-3 and C4-2B, while comparatively lower expression of CaSR is found in non-skeletal metastatic, epithelial-derived prostate cell line LNCaP cells." (PMID 27625611, 2016). "In an immunohistochemical study, comparing human prostate cancer tissue sections in microarrays, CaSR expression was confirmed not only in primary prostate cancer tissue, but also in normal prostate tissue." (PMID 27625611, 2016). "In bone metastatic breast and prostate cancer cells, calcium and CaSR induces proliferation and motility." (PMID 24576174, 2014). "This can explain why prostate cancers expressing high levels of the CaSR are more likely to metastasize to bone than those poorly expressing the CaSR." (PMID 23340319, 2013). "In prostate cancers, calcium-mediated CaSR activation was reported to prevent apoptosis, and to stimulate cell proliferation, and to increase production of PTH-related protein (PTHrP), a causal factor in bone metastasis." (PMID 19602280, 2009). "On the other hand, CaSR activation could facilitate bone metastasis in breast, kidney and prostate cancer." (PMID 32252342, 2020). "Taken together, these results suggest that the CaSR may have a role in promoting metastasis of prostate cancer to bone." (PMID 27303307, 2016). "Importantly, CaSR expression in primary prostate cancers of patients with metastases to tissues other than bone was not different from that in primary prostate cancer of patients with or without bony metastases." (PMID 27303307, 2016). "A few clinical studies supported the notion that CaSR promotes lethal prostate cancer." (PMID 27625611, 2016). "However, a significant higher expression level of CaSR was found in the metastatic prostate cancer tissues obtained from bone." (PMID 27625611, 2016). "Prostate cancer: The CaSR is expressed on human prostate cancer cell lines." (PMID 23340319, 2013). "In fact, a functional CaSR was detected in human prostate cancer cells." (PMID 19602280, 2009). "Furthermore, activation of CaSR triggered prostate cancer cells’ attachment, but the mechanism remains unknown." (PMID 36071984, 2022). "Collectively, the CaSR-mediated effects on prostate cancer metastasis to the bone provide a mechanistic framework in which to study the potential prognostic markers and therapeutic targets that may be associated with the reviewed epidemiologic dependence on calcium intake." (PMID 29921791, 2018). "Considering the important role that TRPV6 and CaSR have in cancer, we undertook these pilot experiments to investigate the MEMRI response in different types of breast and prostate cancer animal models, characterized by different level of expression of these molecules." (PMID 32931488, 2020). "Similar to CaSR expression in metastatic prostate cancers, β1-containing integrins have been shown to be constitutively activated in prostate cancer cell lines with high metastatic potential, but not in cancer cell lines with low metastatic potential." (PMID 27303307, 2016). "Consistently, in this study, we provided the first evidence that R-568 but not its negative isomer S-568 induces apoptotic cell death in human prostate cancer cells, and that R-568-induced cell death is via a CaSR-dependent pathway." (PMID 19602280, 2009).
pancreatitis (19 papers, 2011 to 2025). Inflammation of the pancreas. "Next Generation Sequencing was performed to analyze a panel of nine genes associated with pancreatitis (CaSR, CFTR, CPA1, CTRC, CTSB, KRT8, PRSS1, PRSS2, and SPINK1)." (PMID 38927485, 2024). "Individuals who underwent germline multigene testing for pancreatitis susceptibility genes (CASR, CFTR, CPA1, CTRC, PRSS1, SPINK1) through a large commercial laboratory between 2017 and 2022 were included." (PMID 39172977, 2024). "This combined effect of mutations in TRPV6 and CASR would lead to intra-ductal Ca2+ overload, an established causal factor for premature activation of pancreatic enzymes and pancreatitis." (PMID 36699452, 2022). "Mutation in the CASR gene alone or combination with the SPINK1 gene is involved in the cause of pancreatitis or pancreatic cancer." (PMID 36275616, 2022). "Mutations in other genes such as anionic trypsinogen (PRSS2), the serine protease inhibitor Kazal type 1 (SPINK1), CFTR, chymotrypsinogen C (CTRC) and calcium-sensing receptor (CASR) are also associated with an increased risk for pancreatitis." (PMID 22133269, 2011). "Mutation of CASR gene alone or in combination with SPINK1 gene mutation can lead to pancreatitis." (PMID 36275616, 2022). "However, both loss and gain-of-function mutations of the CASR gene have been associated with pancreatitis, and recent studies even suggest that variants do not modify the risk for chronic pancreatitis." (PMID 36699452, 2022). "However, FHH1 probands with pancreatitis typically harbour heterozygous mutations of both the CASR and serine protease inhibitor, Kazal type 1 (SPINK1) genes." (PMID 26082470, 2015). "We investigated the expression of pancreatitis-associated genes with the ability to act as positive regulators of the IL-6 amplifier; these genes include GGT1, PRSS1, CASR, CTRB1, ABO, SPINK1, and CTRC." (PMID 38806529, 2024). "Although PVs in CASR and CPA1 have been identified as pancreatitis risk factors in some patients, the majority of described variants in these genes provide a minor contribution to the pathogenesis of CP." (PMID 39172977, 2024). "At least five genes have been identified to be associated with pancreatitis: serine protease 1 (PRSS1), serine peptidase inhibitor Kazal type 1 (SPINK1), CFTR, chymotrypsin C (CTRC), and calcium sensing receptor (CASR)." (PMID 35844741, 2022). "Mutations in PRSS1, SPINK1, CTRC, CASR, and CFTR were linked with pancreatitis and pancreatic cancers when the molecular basis of pancreatitis was investigated." (PMID 36434531, 2022). "Other genetic factors related to pancreatitis are Calcium Sensing Receptor (CASR), Claudin 2 (CLDN2), Carboxyl Ester Lipase (CEL), Cathepsin B (CTSB), Myosin IXB (MYO9B), Ubiquitin Protein Ligase E3 Component N-Recognin 1 (UBR1), and Fucosyltransferase 2 (FUT2)." (PMID 36434531, 2022). "CASR, first characterized in the bovine parathyroid, expressed in the pancreas can respond to high calcium concentrations in the pancreatic juice by increasing ductal fluid secretion, thereby preventing stone formation and pancreatitis." (PMID 33375361, 2020). "CaSR also inhibits cell proliferation in pancreatic cancer, and CaSR mutations, with or without SPINK1, cause pancreatitis." (PMID 36275616, 2022). "In the following years, loss-of-function variants in the pancreatic secretory trypsin inhibitor (SPINK1), calcium-sensing receptor (CASR) and chymotrypsinogen C (CTRC) genes, firmly established the pivotal role of prematurely activated trypsin within the pancreas in the etiology of pancreatitis." (PMID 30134826, 2018).
Hypocalciuria (18 papers, 2010 to 2025). An abnormally decreased calcium concentration in the urine. "CaSR mutations also increase calcium reabsorption in the kidneys, resulting in decreased urinary calcium levels (hypocalciuria)." (PMID 39246902, 2024). "In classic form of this disorder, there is normal or hypocalciuria (Ca/Cr ratio <0.01), as expected when there is a point mutation confined in extracellular and transmembrane domains of CaSR." (PMID 25292184, 2014). "In FHH, renal sensing of serum calcium and downstream effects beyond the CaSR are also abnormal, clinically leading to hypocalciuria or potentially abnormal urinary calcium levels." (PMID 40070587, 2025).
autosomal dominant hypocalcemia type 1 (17 papers, 2015 to 2025). "We examined variants of CASR associated with autosomal-dominant hypocalcemia type 1 (ADH1) and created a score to identify 9 additional variants." (PMID 40664210, 2025). "Heterozygous activating mutations in CASR cause Autosomal Dominant Hypocalcemia, type 1 (ADH1), or Bartter’s Syndrome, type V (both OMIM# 601198)." (PMID 37377737, 2023). "Activating mutations in CASR cause autosomal dominant hypocalcemia type 1 (ADH1), alternatively termed familial hypercalciuric hypocalcemia." (PMID 36812896, 2023). "CASR loss- or gain-of-function mutations cause familial hypocalciuric hypercalcemia type 1 (FHH1) or autosomal-dominant hypocalcemia type 1 (ADH1), respectively, but the population prevalence of FHH1 or ADH1 is unknown." (PMID 32386559, 2020). "Activating mutation of the calcium-sensing receptor gene (CASR) reduces parathyroid hormone secretion and renal tubular reabsorption of calcium, defined as autosomal dominant hypocalcemia type 1 (ADH1)." (PMID 36812896, 2023). "In contrast, germline gain-of-function mutations of CASR (MIM: 601198) and GNA11 (MIM: 615361) cause autosomal-dominant hypocalcemia types 1–2 (ADH1-2), respectively." (PMID 32386559, 2020). "Autosomal dominant hypocalcemia types 1 and 2 (ADH1 and ADH2) are caused by germline gain-of-function mutations of the calcium-sensing receptor (CaSR) and its signaling partner, the G-protein subunit α 11 (Gα 11), respectively." (PMID 31820785, 2020).
hyperphosphatemia (17 papers, 2010 to 2025). Abnormally high level of phosphate in the blood. "Previous studies have suggested that SHPT is associated with hyperphosphatemia, CaSR, vitamin D receptor, fibroblast growth factor-23, down-regulation of PTH receptor expression, reduced target organ responsiveness to PTH, PTH metabolic disorders, and regulation of miRNAs." (PMID 40394480, 2025). "The pathogenesis of SHPT is complex, and previous studies have suggested a link to hyperphosphatemia, CaSR, and endocrine cell proliferation." (PMID 40394480, 2025). "These IC50 values for Pi indicate CaSR sensitivity to Pi both over its physiological range (0.8–1.4 mM), and also sensitivity to the hyperphosphatemia of CKD, indicating the potential pathophysiological relevance of this effect." (PMID 31619668, 2019). "There is emerging evidence that phosphate also has a direct effect on the parathyroid glands and CaSR, in that hyperphosphataemia directly inhibits CaSR activity which, in turn, stimulates PTH secretion and thus promotes renal phosphate wasting from the proximal renal tubule." (PMID 33614549, 2021). "In addition, it has been shown that FGF23, in an αKlotho-dependent manner, suppresses PTH secretion, which is reduced in CKD and that the CaSR suppressive effect is also reduced because of hyperphosphatemia-related decreased expression of the CaSR." (PMID 33416083, 2021). "Indeed, hyperphosphatemia (2 mM Pi) significantly reduced the maximal CaSR-induced pERK in CaSR-HEK cells by 30% and this inhibitory effect was again maintained in acidic conditions (pH 7.2)." (PMID 31619668, 2019). "To assess whether the rise in PTH secretion observed in hyperphosphatemia was mediated by the CaSR, we compared PTH secretion levels from control and CaSR-knockout (KO Casr) murine parathyroid glands." (PMID 31619668, 2019). "In vascular smooth muscle cells, the effect of hyperphosphatemia on ORAI1/STIM1 expression and SOCE is suppressed by Mg2+ and the calcium-sensing receptor (CaSR) agonist Gd3+." (PMID 33804889, 2021). "Then in the hyperphosphatemia of CKD, Pi-mediated stabilization of the CaSR’s inactive conformation would elicit chronically increased PTH release as the damaged kidneys fail to excrete the Pi, leading to SHPT, and in turn to further bone loss and hyperphosphatemia." (PMID 31619668, 2019). "Specifically, by increasing extracellular Pi, at concentrations observed in CKD, we demonstrate that hyperphosphatemia inhibits the CaSR in a noncompetitive manner and thus increases PTH secretion." (PMID 31619668, 2019). "In addition, CaSR has been observed as a phosphate receptor in the parathyroid gland, and hyperphosphatemia, as a non-competitive inhibitor, inhibits its activity, thereby enhancing PTH production." (PMID 36267284, 2022).